MCCD1 (mitochondrial coiled-coil domain 1)
Tractability: No criterion of Open Targets' tractability assessment is met for any kind of drug.
Gene: Protein-coding gene on chromosome 6 (31,528,962 to 31,530,232, forward strand). Ensembl gene ENSG00000204511.
Subcellular location: Mitochondrion
Gene Ontology:
Molecular function: protein binding
Cellular component: mitochondrion
Genetic constraint (gnomAD): Loss-of-function variants: 5 observed, 4.65 expected, observed/expected ratio (o/e) 1.07, 90% interval 0.55 to 1.84. That is too few expected variants to judge how well the gene tolerates losing a copy. Missense variants: 178 observed, 131.3 expected, observed/expected ratio (o/e) 1.36, 90% interval 1.2 to 1.53. Synonymous variants: 70 observed, 51.95 expected, observed/expected ratio (o/e) 1.35, 90% interval 1.11 to 1.64.
Homologues: Orthologues: chimpanzee MCCD1 (99% identical), macaque MCCD1 (94% identical), pig MCCD1 (69% identical).
Diseases named in the same sentence as MCCD1 in open-access papers:
MCCD1 is named in the same sentence as 3 diseases in open-access papers, as found by Europe PMC text mining. Sharing a sentence is not in itself a finding about the gene and the disease. The quoted sentences say what the papers report.
clear cell renal carcinoma (1 paper, 2022). A malignant epithelial neoplasm of the kidney characterized by the presence of lipid-containing clear cells within a vascular network. "We identified five survival-related genes (AGR2, HAO2, IGF2BP1, MCCD1 and OLFM4) in clear cell renal carcinoma patients." (PMID 36516496, 2022).
leprosy (1 paper, 2016). Leprosy is a chronic infectious disease affecting primarily the skin and peripheral nervous system. "The protein interaction network analysis supported this speculation, as we found that the other mitochondrial genes (MCCD1, SDHD, SNCA, and VARS2) could interact with the reported leprosy susceptibility genes." (PMID 27876828, 2016).
MCCD1 also shares sentences with these, for which no sentence is quoted: cholelithiasis (1 paper).